CFTR (CF transmembrane conductance regulator)
Diseases named in the same sentence as CFTR in open-access papers (continued):
Sharing a sentence is not in itself a finding about the gene and the disease.
cystic fibrosis (continued). "Cystic fibrosis is a genetic disorder caused by mutations in the gene encoding the cystic fibrosis transmembrane conductance regulator (CFTR), a selective anion channel expressed in the epithelium of various organs." (PMID 38396982, 2024). "Cystic fibrosis is a life-limiting, multisystemic, autosomal recessive disease caused by various mutations in the gene responsible for encoding the cystic fibrosis transmembrane conductance regulator (CFTR) gene." (PMID 39057346, 2024). "Most individuals with CF, a genetic disorder caused by mutations in the cystic fibrosis transmembrane conductance regulator (CFTR) gene, are colonized by P. aeruginosa, which represent the major cause to morbidity and mortality in these patients." (PMID 39596075, 2024). "Cystic fibrosis is a genetic disorder resulting from mutations in the cystic fibrosis transmembrane conductance regulator (CFTR) gene that affect the digestive system and respiratory tracts." (PMID 38612771, 2024). "CF is a disease caused by the mutation in the cystic fibrosis transmembrane conductance regulator (CFTR) ion channel." (PMID 39513856, 2024). "People with CF, who have mutations in their cystic fibrosis transmembrane conductance regulator (CFTR) gene encoding an anion channel, have a reduced ASL pH, and their airway mucus becomes much thicker and more viscous." (PMID 38674677, 2024). "CF is a rare disease caused by a deficiency in the synthesis of the Cystic Fibrosis Transmembrane Conductance Regulator (CFTR) channel protein, resulting in multi-organ clinical symptoms, particularly in the respiratory system." (PMID 38541936, 2024). "The incidence of CF depends on the prevalence of cystic fibrosis transmembrane conductance regulator gene (CFTR) mutations in the population, which is determined by genetic diversity and ethnicity." (PMID 39457459, 2024). "Recent studies have shown that CF is caused by mutations in the gene encoding the cystic fibrosis transmembrane conductance regulator (CFTR), and CFTR potentiators have been shown to be useful in reducing disease progression in patients with CF." (PMID 39329117, 2024). "CF is a genetic disorder caused by mutations in the gene encoding the epithelial chloride channel of the cystic fibrosis transmembrane conductance regulator (CFTR)." (PMID 38474149, 2024). "CF is caused by a decreased quantity and/or function of the cystic fibrosis transmembrane regulator (CFTR) protein." (PMID 39408020, 2024). "We tested whether the random forest models trained on endogenous mRNA features and transcriptome-wide readthrough efficiency measured by ribosome profiling can accurately predict the readthrough efficiency of 15 PTCs derived from CFTR nonsense alleles that are found in cystic fibrosis patients." (PMID 38509072, 2024). "Mutations in the cystic fibrosis transmembrane conductance regulator (CFTR) gene cause cystic fibrosis, a multiorgan disease that is characterized by diverse metabolic defects." (PMID 38743489, 2024). "This phenotype is typically observed in cystic fibrosis, a genetic disease caused by dysfunction of the CFTR anion channel." (PMID 38336456, 2024). "CF is caused by a defect in the cystic fibrosis transmembrane conductance regulator (CFTR), which leads to dysregulation of ion and water flow and an accumulation of thick, sticky mucus at mucosal surfaces." (PMID 38179971, 2024). "Cystic fibrosis is a genetic disorder caused by mutations in a gene that encodes a chloride-conducting transmembrane channel called the CF transmembrane conductance regulator (CFTR)." (PMID 38416239, 2024). "Cystic fibrosis, one of the most frequent genetic diseases, is caused by loss-of-function variants in the CFTR gene." (PMID 39624835, 2024). "Cystic fibrosis is an autosomal recessive genetic disorder characterized by impairment of the CF transmembrane conductance regulator (CFTR) via gene mutation." (PMID 39681187, 2024).
cystic fibrosis (continued). "Cystic Fibrosis is a disease arising from mutations in the CFTR (cystic fibrosis transmembrane conductance regulator) gene and is characterized by impaired ion transport across epithelial cell membranes and consequent accumulation of mucus in airways." (PMID 39286289, 2024). "In CF patients, mutations in the cystic fibrosis transmembrane conductance regulator (CFTR) result in increased materials that promote bacterial adhesion to epithelial cells." (PMID 39523331, 2024). "The cystic fibrosis occur due to the mutations in the CFTR gene as it produces the dysfunctional CFTR protein." (PMID 39043981, 2024). "The monogenic rare disease Cystic Fibrosis is caused by mutations in the gene encoding the CF transmembrane conductance (CFTR) protein, an anion channel expressed at the apical plasma membrane of epithelial cells." (PMID 38398574, 2024). "CF is caused by pathogenic variants in the cystic fibrosis transmembrane conductance regulator (CFTR) gene located on the long arm of human chromosome 7 (7q31.2)." (PMID 38398033, 2024). "Cystic Fibrosis is a genetic disease caused by mutations in CFTR gene expressing the anion selective channel CFTR located at the plasma membrane of different epithelial cells." (PMID 38888668, 2024). "Cystic fibrosis is a prevalent autosomal-recessive disorder caused by mutations in the cystic fibrosis transmembrane conductance regulator (CFTR) gene, affecting more than 30,000 individuals in the United States and over 160,000 globally, based on estimates." (PMID 39507496, 2024). "Cystic fibrosis is a monogenic autosomal recessive disease that results from deleterious variants of the Cystic Fibrosis Transmembrane Conductance Regulator (CFTR) gene." (PMID 39606224, 2024). "Cystic fibrosis is a monogenic disease caused by mutations in the CF transmembrane conductance regulator (CFTR) gene." (PMID 38725656, 2024). "In 1989, our lab huddled around our fax machine as it rolled out Lap-Chee Tsui, Francis Collins, and their colleagues’ paper identifying the gene that is mutated in CF — cystic fibrosis transmembrane conductance regulator (CFTR)." (PMID 39352390, 2024). "Cystic fibrosis is an autosomal recessive genetic condition caused by mutations in the cystic fibrosis transmembrane conductance regulator (CFTR) gene." (PMID 37877879, 2023). "Respiratory infections are a hallmark of cystic fibrosis, a heritable, autosomal disease caused by mutations in the cystic fibrosis transmembrane conductance regulator (CFTR) gene." (PMID 37512880, 2023). "Cystic fibrosis is an autosomal recessive disease caused by mutations in the cystic fibrosis transmembrane conductance regulator (CFTR) gene coding for the chloride channel situated in the apical membrane of epithelial cells of exocrine tissue." (PMID 37762950, 2023). "Similar methods were used for cystic fibrosis, a disease characterized by significant pulmonary and pancreatic dysfunctions and is a result of mutations in the CFTR gene, coding for a Cl- channel." (PMID 36792602, 2023). "CF is a genetic disease that originates from mutations in the Cystic Fibrosis Transmembrane Conductance Regulator (CFTR) gene." (PMID 37767091, 2023). "Cystic fibrosis is a monogenic disorder caused by loss-of-function of the CF transmembrane conductance regulator (CFTR), a chloride and bicarbonate channel expressed in respiratory, gastrointestinal, and exocrine tissues (among others)." (PMID 37168508, 2023). "Cystic fibrosis is an autosomal recessive disorder caused by mutations in the human cystic fibrosis transmembrane conductance regulator (CFTR) gene, which is located on the long arm of chromosome 7 (7q31.2)." (PMID 36833376, 2023). "Cystic fibrosis is a rare autosomal recessive disease caused by mutations in the cystic fibrosis transmembrane conductance regulator (CFTR) gene." (PMID 36923406, 2023).
cystic fibrosis (continued). "Cystic fibrosis is a rare multi-organ, autosomal recessive disease caused by mutations of the Cystic Fibrosis Transmembrane Conductance Regulator (CFTR) gene, located in the long arm of chromosome 7 and grouped in five classes." (PMID 37957647, 2023). "As a clear example, mutations in the chloride channel CFTR, an ionocyte marker, give rise to cystic fibrosis." (PMID 36864051, 2023). "CF is a multisystemic disease due to mutations in the cystic fibrosis trans-membrane conductance regulator (CFTR) gene, and it mostly affects the respiratory system but also the pancreas, liver, kidneys and intestine." (PMID 37892370, 2023). "Cystic fibrosis is the most prevalent autosomal recessive genetic condition that is caused by a defect in the cystic fibrosis transmembrane conductance regulator (CFTR) protein and forms a chloride and bicarbonate channel." (PMID 37110338, 2023). "Cystic Fibrosis is a rare autosomal recessive disease caused by mutations in the CF Transmembrane Conductance Regulator (CFTR) gene, which encodes an epithelial chloride and bicarbonate transport channel." (PMID 36975847, 2023). "Cystic fibrosis is a common autosomal recessive disorder among Caucasians caused by mutations in the gene that encodes the CF transmembrane conductance regulator." (PMID 37585917, 2023). "Cystic fibrosis is a life-limiting autosomal recessive disorder due to variants in the Cystic Fibrosis Transmembrane Conductance Regulator (CFTR) gene." (PMID 37679850, 2023). "Recent developments in CFTR modulator drugs have had a significant transformational effect on the treatment of individuals with Cystic Fibrosis who carry the most frequent F508del-CFTR mutation in at least one allele." (PMID 37371529, 2023). "Cystic fibrosis is characterized by mutations of CFTR that lead to increased viscous secretions, bacterial colonization, and recurrent infections." (PMID 36602344, 2023). "CF is an autosomal recessive genetic disorder resulting from mutations in the cystic fibrosis transmembrane conductance regulator (CFTR) gene." (PMID 37795866, 2023). "Cystic fibrosis, an autosomal genetic disorder caused by the dysfunction of the cystic fibrosis transmembrane conductance regulator (CFTR) protein, is characterized by mucus accumulation in the lungs, the intestinal tract, and the pancreatic ducts." (PMID 36117114, 2023). "Cystic fibrosis is an autosomal recessive multi-system disease, which results from mutations in the CF transmembrane conductance regulator (CFTR) gene." (PMID 37229253, 2023). "The majority of CF cases are due to an inherited mutation in phenylalanine residue 508 of a specific chloride ion channel, named the cystic fibrosis transmembrane conductance regulator (CFTR)." (PMID 38173971, 2023). "Cystic fibrosis is an autosomal recessive genetic disease caused by mutations of the CF Transmembrane conductance Regulator (CFTR) gene, which encodes an integral membrane ion transporter." (PMID 36902441, 2023). "Cystic fibrosis is an autosomal recessive disorder caused by mutations in the gene encoding the CF transmembrane conductance regulator (Cftr)." (PMID 37108362, 2023). "Cystic fibrosis is a genetic disease caused by a mutation leading to the complete or partial loss-of-function of the CF transmembrane conductance regulator (CFTR), a protein responsible for ion transport across apical membranes of epithelial cells." (PMID 37648735, 2023). "CF is caused by mutations in the cystic fibrosis transmembrane conductance regulator (CFTR) gene, located at 7q31.2, which encodes the CFTR protein." (PMID 36771186, 2023). "The advent of cystic fibrosis transmembrane conductance regulator modulator (CFTRm) drugs has revolutionized the treatment of cystic fibrosis in individuals with drug-responsive CFTR variants." (PMID 37050905, 2023).
cystic fibrosis (continued). "CF is caused by mutations in the cystic fibrosis transmembrane conductance regulator (CFTR) gene, which codes for a chloride channel found in various tissues, including the airway epithelial cells, pancreatic ducts, and sweat glands." (PMID 37887299, 2023). "F508del, the most frequent mutation in cystic fibrosis, impairs the stability and folding of the CFTR chloride channel, thus resulting in intracellular retention and CFTR degradation." (PMID 37165082, 2023). "Cystic fibrosis is an autosomal recessive inherited disorder, which involves mutations of the cystic fibrosis transmembrane conductance regulator (CFTR, OMIM 602,421) gene on chromosome 7." (PMID 37489040, 2023). "Disruption of CFTR in mice causes organ diseases typical of cystic fibrosis, such as meconium ileus, distal intestinal obstructions with mucus accumulation, blockage of pancreatic ducts and lacrimal gland dilatation, along with some developmental defects." (PMID 37686084, 2023). "CF is a genetic disorder resulting from point mutation of the cystic fibrosis transmembrane conductance regulator (CFTR) gene." (PMID 38274738, 2023). "Cystic fibrosis is an autosomal recessive disease caused by mutations in a gene encoding a cystic fibrosis transmembrane conductance regulator (CFTR) protein." (PMID 36978351, 2023). "CF is caused by mutations in the Cystic Fibrosis Transmembrane Conductance Regulator (CFTR) gene, which encodes a 1480 amino acid-long membrane protein expressed in the apical membrane of epithelial cells." (PMID 36834620, 2023). "Cystic fibrosis is a genetic disorder caused by mutations affecting an epithelial ion transporter, the cystic fibrosis transmembrane conductance regulator (CFTR)." (PMID 36748431, 2023). "It is reported that about 10% of cystic fibrosis patients worldwide have nonsense (stop) mutations in the CFTR gene, which cause the premature termination of CFTR protein synthesis, leading to a truncated and non-functional protein." (PMID 37446121, 2023). "Cystic fibrosis is the most common severe autosomal recessive genetic disease in Caucasians caused by a mutation of the cystic fibrosis transmembrane conductance regulator (CFTR) gene." (PMID 36678185, 2023). "Cystic fibrosis is a genetic disease caused by a mutation in the cystic fibrosis transmembrane conductance regulator (CFTR) gene." (PMID 37199622, 2023). "CF is characterized by abnormal ion transport due to mutations in the cystic fibrosis transmembrane conductance regulator (CFTR) gene." (PMID 37686519, 2023). "Cystic fibrosis is a genetic disease caused by mutations of the gene coding for the CS transmembrane conductance regulator (CFTR) anion channel." (PMID 36602863, 2023). "An Italian, 46-year-old female patient carrying the complex allele p.[R74W;V201M;D1270N] in trans with CFTR dele22_24 was diagnosed at the Cystic Fibrosis Center of Verona as being affected by CF-pancreatic sufficient (CF-PS) in 2021." (PMID 36982273, 2023). "Cystic fibrosis is characterized by a mutation in the transmembrane conductance regulator protein (CFTR) that results in a thick mucous layer and impairment of immune function." (PMID 37713457, 2023). "In the inherited disorder cystic fibrosis, loss of cystic fibrosis transmembrane conductance regulator (CFTR) anion channel function reduces HCO3− secretion, lowers the pH of ASL (pHASL), and impairs host defenses." (PMID 37190013, 2023). "Lumacaftor-ivacaftor is a cystic fibrosis transmembrane conductance regulator (CFTR) modulator combination approved for patients with cystic fibrosis who are homozygous for the F508del allele." (PMID 36971560, 2023). "Cystic fibrosis, the result of mutations in the CF transmembrane conductance regulator (CFTR), causes essential fatty acid deficiency." (PMID 37108362, 2023). "Cystic fibrosis is an autosomal recessive, monogenetic disorder caused by mutations within the cystic fibrosis transmembrane conductance regulator (CFTR) gene located on chromosome 7." (PMID 38117289, 2023).
cystic fibrosis (continued). "Cystic fibrosis is a life-limiting condition caused by mutations in the CF transmembrane conductance regulator (CFTR)." (PMID 37349833, 2023). "Cystic fibrosis is a life-threatening genetic disease caused by mutations of the CF transmembrane conductance regulator (CFTR) gene." (PMID 37720540, 2023). "One of the well‐known causes of bronchiectasis is cystic fibrosis, caused by pathogenic variants in the cystic fibrosis transmembrane conductance regulator (CFTR) gene." (PMID 37323158, 2023). "CF is related to mutations in the cystic fibrosis transmembrane conductance regulator (CFTR) gene, which encodes the CFTR epithelial ion channel involved in chloride and bicarbonate transport, leading to impaired mucus hydration and clearance." (PMID 36911035, 2023). "CF is an autosomal recessive disease caused by a mutation in the cystic fibrosis transmembrane conductance regulator (CFTR) gene on chromosome 7." (PMID 37554905, 2023). "Cystic fibrosis is caused by homozygous recessive mutations in the cystic fibrosis transmembrane conductance regulator (CFTR) gene." (PMID 37841851, 2023). "Cystic fibrosis, caused by pathogenic variants in the cystic fibrosis transmembrane conductance regulator (CFTR) gene has been a success story in personalized medicine." (PMID 37323158, 2023). "Cystic Fibrosis is a genetic disorder caused by mutations in the cystic fibrosis transmembrane regulator (CFTR) gene, encoding for CFTR protein, an important chloride channel of exocrine glands." (PMID 37108596, 2023). "CF is an autosomal recessive disease caused by a genetic mutation of the gene encoding the cystic fibrosis transmembrane conductance regulator (CFTR)." (PMID 37760016, 2023). "Cystic fibrosis is a hereditary condition stemming from mutations in the cystic fibrosis transmembrane conductance regulator (CFTR) gene." (PMID 38004561, 2023). "CF is an autosomal recessive disorder, in which patients showed genetic variants of cystic fibrosis transmembrane conductance regulator (CFTR) gen, which translates the CFTR protein." (PMID 37887299, 2023). "CF develops in the presence of two inactivating germline mutations in the CFTR gene encoding the protein of the same name, CFTR (cystic fibrosis transmembrane conductance regulator)." (PMID 37175647, 2023). "The molecular basis of CF lies in the occurrence of mutations in the cystic fibrosis transmembrane conductance regulator (CFTR) gene, with an autosomal recessive inheritance." (PMID 37628659, 2023). "Formerly called mucoviscidosis, CF is an autosomal recessive genetic disease caused by mutations in the CFTR (Cystic Fibrosis Transmembrane Regulator) gene." (PMID 36902066, 2023). "Cystic Fibrosis is a genetic disorder caused by null mutations in the cystic fibrosis transmembrane conductance regulator (CFTR) gene, which encodes for the chloride channel." (PMID 36611992, 2023). "CF is an autosomal recessive genetic disease caused by mutations in the cystic fibrosis transmembrane conductance regulator (CFTR) gene." (PMID 38136665, 2023). "The incidence of cystic fibrosis and the spectrum of cystic fibrosis transmembrane conductance regulator (CFTR) gene variants differ among geographic regions." (PMID 37628659, 2023). "Cystic fibrosis is caused by impaired mucociliary airway clearance due to a mutation in the cystic fibrosis transmembrane conductance regulator (CFTR) gene." (PMID 37765701, 2023). "CF is a life-limiting disease caused by mutations in the cystic fibrosis transmembrane conductance regulator (CFTR) gene." (PMID 38149052, 2023). "CF is a life‐limiting autosomal recessive disease, caused by mutations in the cystic fibrosis transmembrane conductance regulator (CFTR) gene." (PMID 37269165, 2023). "Cystic Fibrosis is a lethal autosomal recessive disease characterized by mutations in the CF transmembrane conductance regulator (CFTR) gene." (PMID 36834512, 2023).